CDKAL1 (CDKAL1 threonylcarbamoyladenosine tRNA methylthiotransferase)
Diseases named in the same sentence as CDKAL1 in open-access papers (continued):
Sharing a sentence is not in itself a finding about the gene and the disease.
diabetes (continued). "A study in a Chinese Han population reported an OR of 1.47 (95% CI 1.25‐1.73) for the association of rs10946398 in CDKAL1 with diabetes, which is similar to the findings of the present study (OR 1.59; 95% CI 1.21‐2.08)." (PMID 30907055, 2019). "Among such SNPs, variants at TCF7L2 and CDKAL1 have also been associated with increased risk of cancer in people with diabetes, potentially explaining the higher mortality risk for low BMI values." (PMID 27888288, 2017). "We also replicated the diabetes susceptibility variant rs10946398 in CDKAL1 (OR: 1.2, P = 7.1*10−4)." (PMID 20161779, 2010). "Psoriasis and diabetes are also linked to the pleiotropic susceptibility locus CDKAL1." (PMID 40660159, 2025). "Interestingly, several polymorphic variants (rs7756992, rs7754840, and rs10946398) are also located in the non-coding region of the CDKAL1 locus, which is strongly associated with an increased risk of developing diabetes among those with European ancestry." (PMID 39561140, 2024). "The CDKAL1 genetic variants could predict the development of diabetes in individuals with impaired insulin secretion, which indicates that there may be potential synergistic and interactive effects among different risk factors." (PMID 36183068, 2022). "For example, the pleiotropic susceptibility loci CDKAL1 contributes to the occurrence of psoriasis as well as diabetes mellitus, which may upregulate the inflammatory cytokines in psoriasis promoting insulin resistance, an independent risk factor of T2DM." (PMID 34803716, 2021). "Pleiotropic susceptibility loci CDKAL1 contributes to the occurrence of psoriasis as well as diabetes mellitus, which may upregulate inflammatory cytokines in psoriasis and thus promote insulin resistance, an independent risk factor of T2DM." (PMID 34803716, 2021). "CDKAL1 variants play a significant role in diabetes, and dietary protein and fat intake could impact their function." (PMID 32764395, 2020). "We found that subjects with CC or CG genotypes at the CDKAL1 (rs7754840) locus had increased waist circumstance and waist/hip ratio, indicating that rs7754840 may increase diabetes risk as well as abdominal obesity." (PMID 32228543, 2020). "Dietary factors that affect insulin demand might enhance the risk of diabetes associated with CDKAL1 variants." (PMID 32764395, 2020). "CDKAL1 is a strong gene identified so far as being significantly associated with diabetes." (PMID 32764395, 2020). "Dietary factors play a role in the relationship between CDKAL1 polymorphism and diabetes." (PMID 32764395, 2020). "However, only limited studies have evaluated the interactions between dietary protein and fat intake and CDKAL1 genetic variations in relation to the risk of diabetes." (PMID 32764395, 2020). "Individual genes associated with psoriasis, such as CDKAL1, are also associated with diabetes." (PMID 23843781, 2013). "Defects in this process caused by decreased CDKAL1 expression levels may confer an increased risk of diabetes." (PMID 21151568, 2010). "Thus, the altered expression of CDKAL1 is probably associated with reduced glucose-induced first-phase insulin exocytosis and thus confers an increased risk for diabetes." (PMID 21151568, 2010). "Thus, Cdkal1 has been found to be a potentially important factor in determining whether a patient is at a high risk for diabetes." (PMID 33634165, 2020). "For example, instruments are from genes TCF7L2, IGF2BP2, NOTCH2, CDKAL1, PABPC4, FTO and JAZF1, known to be associated with diabetes and that have been further significantly associated with the metabolites." (PMID 39349772, 2024). "The link between psoriasis and diabetes could, in part, be explained by the rise in obesity and unhealthy lifestyles, the insulin resistance associated with inflammation, and the presence of various genes (CDKAL1, PTPN22, ST6GAL1, JAZF1) linked to both conditions." (PMID 38541672, 2024).
diabetes (continued). "We examined the association between CDKAL1 rs10946398, GCK rs1799884, GCKR rs780094 and DGKB/TMEM195 rs2191349 gene polymorphisms and the development of post-transplant diabetes in kidney transplant patients treated with tacrolimus." (PMID 37628646, 2023). "CDKAL1, as a mechanism-related protein for diabetes, is related to the defects of proinsulin conversion and insulin response under glucose stimulation." (PMID 36183068, 2022). "As autophagy is also strongly suggested to be associated with the pathogenesis of metabolic diseases including diabetes, the interaction between CDKAL1 and ATG5 could exist." (PMID 26509176, 2015). "We aimed to characterise the possible longitudinal associations of common diabetes-susceptibility variants in the KCNJ11, PPARG, TCF7L2, IGF2BP2, CDKAL1, SLC30A8 and HHEX gene loci, with fasting glucose level; and of an obesity-associated variant in the FTO gene, with body mass index (BMI)." (PMID 20929593, 2010). "Similarly, genes ABCB11 (chromosome 2), ADCY5 (chromosome 3), CDKAL1 (chromosome 6), ANK1 (chromosome 8), GLIS3 (chromosome 9), and HKDC1 (chromosome 10) have been linked to various aspects of diabetes, including insulin release, glucose levels, β-cell function, and insulin resistance." (PMID 38274506, 2023). "Here, we demonstrate that CDKAL1 is required for kidney function and that its dysfunction directly promotes CKD progression independently of diabetes." (PMID 41904323, 2026). "In total, of the top five association signals that were mapped to genes (n = 103) we found five (CDKAL1, DCDC2C, KLF12, LPIN2, TLE1) to be related with diabetes." (PMID 31818369, 2019). "CDKAL1 was revealed to be an inhibitor of CDK5 to suppress the β-cell differentiation and further highlighted its importance in diabetes." (PMID 31098383, 2019). "The aim of this study was to evaluate the association of selected polymorphisms of genes affecting carbohydrate metabolism, such as CDKAL1 rs10946398, GCK rs1799884, GCKR rs780094 and DGKB/TMEM195 rs2191349, with the development of post-transplant diabetes in kidney transplant patients." (PMID 37628646, 2023). "The associations of 23 SNPs located within 17 candidate genes (MTHFR, PPARγ, LPL, INSIG, TCF7L2, FTO, KCNJ11, JAZF1, CDKN2A/B, ADIPOQ, WFS1, CDKAL1, IGF2BP2, KCNQ1, MTNR1B, IRS1, ACE) with overweight and obesity, diabetes, metabolic phenotypes, and MetS were examined in both studies." (PMID 24959828, 2014). "Interestingly, our study showed no strong CDKAL1 association with the MOD cluster, underscoring the specificity of this gene’s role in insulin-deficient diabetes." (PMID 41422334, 2025). "In summary, CDKAL1 and GIPR-QPCTL loci showed the strongest associations with beta-cell glucose sensitivity by genome-wide and candidate gene-based approaches, and these associations were independent of diabetes status." (PMID 32944759, 2021). "CDKAL1, RREB1, and PPARG were not significant in either arm of the diabetes stratified analysis, while RAI1 and SLC9B2 were significant in the non-diabetes group." (PMID 31451708, 2019).
Obesity (29 papers, 2007 to 2025). Accumulation of substantial excess body fat. "Located on chromosome 6p22.3, the CDKAL1 gene is closely connected to a heightened risk of T2D and obesity." (PMID 39858569, 2024). "Though it has mostly been studied for its downstream effects on the translation of insulin, obesity has also been found to downregulate its mRNA levels in mouse adipose tissue, as CDKAL1 loss affects adipose mitochondrial function." (PMID 36128718, 2022). "Among the 32 probesets, Scd1 is remarkable in that Scd1-deficient mice show the metabolic phenotypes in accordance with those observed in Cdkal1−/− mice; e.g., decreased susceptibility to diet-induced obesity, decreased plasma insulin level, and improved glucose tolerance." (PMID 23173044, 2012). "We found that obesity downregulates Cdkal1 mRNA levels in mouse adipose tissue, spurring us to investigate whether adipocyte-specific loss of Cdkal1 can contribute to obesity-related metabolic disorders in mice on a high fat diet." (PMID 29031721, 2017). "The potential underlying mechanism of Erchen decoction for the treatment of obesity, hyperlipidemia and fatty liver is to increase the CDKAL1 production, improve islet cell function and insulin level." (PMID 32477116, 2020). "Several obesity susceptibility loci in genes, including GNPDA2, SH2B1, TMEM18, MTCH2, CDKAL1, FAIM2, and MC4R, have been identified by genome-wide association studies." (PMID 32228543, 2020). "We identified obesity association for 6 SNPs near SEC16B, RBJ, CDKAL1, TFAP2B, MAP2K5 and FTO (odds ratios (ORs) ranged from 1.19 to 1.41, nominal two-sided P-values < 0.05)." (PMID 26800887, 2016). "FTO rs1421085, CDKAL1 rs2206734, TNNl3K rs1514176, GIPR rs11671664 and the GRS were associated with obesity measures at baseline and/or follow-up." (PMID 26727462, 2016). "With the exception of GAD2 variant rs2236418, none of the candidate variants had been implicated in earlier GWA studies although CDKAL1, CYB5R4, and PPARG loci have been associated with diabetes- and/or obesity-related traits." (PMID 25222615, 2014). "As genetic effects of Cdkal1 deletion on body weight reduction and protection against diet-induced obesity appeared to be rather modest in mice, we should be careful in extrapolating the findings in mice to humans." (PMID 23173044, 2012). "Supporting this, recent studies have shown that CDKAL1 variants are associated with a greater waist circumference and WHR in Chinese populations and serve as independent predictors of metabolically healthy obesity in Chinese children." (PMID 39858569, 2024). "Notably, variants in the CDKAL1, ADCY3, ADRA2A, and NPY2R genes showed strong associations with metabolic traits such as waist circumference, insulin resistance, and obesity." (PMID 39858569, 2024). "In addition, CDKAL1 variants, including rs35612982, are strongly involved in increased T2DM and obesity risk." (PMID 35956399, 2022). "Taken together, among seven common obesity risk loci, the loci near TMEM18 (rs6548238), CDKAL1 (rs7754840), and FAIM2 (rs7138803) are associated with obesity, and loci near TMEM18 (rs6548238) and FAIM2 (rs7138803) are susceptibility loci for obese type 2 diabetes." (PMID 32228543, 2020). "We genotyped nine SNPs reported in GWAS of obesity and/or T2D, including SNPs in HHEX, KCNJ11, SLC30A8, FTO, CDKN2, CDKAL1, TCF2, and the rs9300039 SNP in an intergenic region, in 561 colon cancer cases and 721 population controls." (PMID 27990199, 2009). "GCKR, ABCB11, CDKAL1, CDKN2B, NT5C2, and APOC1 were associated with metabolically unhealthy in individuals with normal weight but not in those with obesity." (PMID 33500527, 2021).
Obesity (continued). "GCKR, ABCB11, CDKAL1, CDKN2B, NT5C2, and APOC1 were associated with metabolically unhealthy phenotypes in individuals with normal weight but not in those with obesity." (PMID 33500527, 2021). "Cdkal1 is also downregulated in inguinal adipose tissue but not liver, suggesting adipose-specific regulation of its expression with obesity." (PMID 29031721, 2017). "We identified the nominally significant associations with obesity for effect alleles of 6 SNPs at FTO, SEC16B, TFAP2B, RBJ, MAP2K5 and CDKAL1 (ORs for the effect allele ranged between 1.19 and 1.41, nominal two-sided P < 0.05)." (PMID 26800887, 2016). "He found GCKR, ABCB11, CDKAL1, CDKN2B, NT5C2, and APOC1 gene were associated with metabolically unhealthy phenotypes in individuals with normal weight but not in those with obesity, showing that certain genetic polymorphisms may also have an impact on the metabolic health in NWO populations." (PMID 39777912, 2025).
Insulin resistance (16 papers, 2012 to 2026). Increased resistance towards insulin, that is, diminished effectiveness of insulin in reducing blood glucose levels. "CDKAL1 rs9295474 exhibited strong association with T2D in multi-ethnic cohorts from Southeast Asia, with its polymorphisms potentially affecting insulin resistance in response to varying levels of dietary fat and protein intake." (PMID 38674857, 2024). "Insulin resistance, a core feature of MetS, is linked to genes such as CDKAL1, ADCY3, and ADRA2A." (PMID 39858569, 2024). "Studies suggest that CDKAL1 polymorphisms may modulate insulin secretion or be related to insulin resistance." (PMID 36183068, 2022). "Thus, it is likely that the copresence of low serum levels of choline and CDKAL1 rs7747752 genetic variant led to a markedly increased risk of GDM via increasing insulin resistance or decreasing insulin sensitivity." (PMID 36183068, 2022). "CDKAL1 polymorphisms may modulate insulin resistance in response to the different levels of dietary fat and protein intake." (PMID 32764395, 2020). "However, among the Greek children, association with insulin resistance could be observed for the two CDKAL1-related SNPs: rs9356744 (β = 0.018, p = 0.014) and rs2206734 (β = 0.024, p = 0.001)." (PMID 24695378, 2014). "Loss-of-function SNPs in the introns of the CDKAL1 gene were found to be associated with defects in insulin secretion but not with obesity or insulin resistance." (PMID 36902173, 2023). "Given the important role of CDKAL1 in proinsulin conversion and insulin resistance, it is of interest to explore whether CKDAL1 genetic variants and low serum levels of L-carnitine, choline, and betaine have synergistic effects on the risk of GDM in Chinese pregnant women." (PMID 36183068, 2022). "The genetic variants related to T2DM in Caucasians are mainly related to insulin resistance, but those in Asians, including Chinese, Japanese, and Koreans, are involved in insulin secretion (GLP1R, PAX4, HNF4A, SLC30A8, HHEX, CDKAL1, CDKN2A/B, and GCKR)." (PMID 35956399, 2022).
psoriasis (15 papers, 2010 to 2025). An autoimmune condition characterized by red, well-delineated plaques with silvery scales that are usually on the extensor surfaces and scalp. "At the 6p22.3 locus, the psoriasis signal tagged by rs4712528 is intronic to CDKAL1, and there were 11 psoriasis-associated intronic fragments that also interacted with the CDKAL1 promoter in My-La cells; CDKAL1 expression was detected in all cells." (PMID 32366252, 2020). "The Cdkal1 locus is linked by GWAS to increased risk of developing the chronic diseases type 2 diabetes, ulcerative colitis, and psoriasis." (PMID 29031721, 2017). "Another investigation examined the genetic signals of T2D and psoriasis around the CDKAL1 locus in Caucasian patients." (PMID 37935955, 2023). "Common genetic variants such as FUT2, UBE2L3, CDKAL1, SH2B3 and apolipoprotein E are more frequently found in psoriasis patients, having multiple functions that would explain their dual role in susceptibility to psoriasis and MS." (PMID 40003621, 2025). "Notably, psoriasis and T2D share genetic and pathological similarities as well as common targets, such as CDKAL1, PSORS2, PSORS3, and PSORS4, which are psoriasis susceptibility genes that are also associated with T2D." (PMID 36362461, 2022). "A pathogenesis involving IL 23R, IL 12B, CDKAL1, and PTPN22 is common to both IBD and psoriasis." (PMID 40981083, 2025). "rs10782001 in FBXL19, rs1975974 in C17orf51, rs12720356 in TYK2, rs3792876 in SLC22A4, rs6908425 in CDKAL1, and rs13437088 in HLA-B/MICA have previously been associated with psoriasis, but not with type I psoriasis." (PMID 26613086, 2015).
gestational diabetes (12 papers, 2018 to 2026). Carbohydrate intolerance first diagnosed during pregnancy. "It was confirmed in different populations, such as Koreans and Russians, that specific genetic variants of CDKAL1 increased susceptibility to type 2 diabetes (T2D) and gestational diabetes mellitus (GDM)." (PMID 40133860, 2025). "Further adjusting for gestational diabetes mellitus, the CDKAL1 genetic marker remained significantly associated with adverse pregnancy outcome, and the OR (95%CI) was 2.52 (1.48, 4.30)." (PMID 40133860, 2025). "Odds ratios of the CDKAL1 rs7747752 and bile acid metabolisms for increased risk of gestational diabetes mellitus." (PMID 35360068, 2022). "Moreover, CDKAL1 is also associated with gestational diabetes." (PMID 39561140, 2024). "The current studies on the relationship between CDKAL1 polymorphisms rs7756992 A>G and rs7754840 C>G and the risk of gestational diabetes mellitus (GDM) have drawn contradictory conclusions." (PMID 34721291, 2021). "Association of single nucleotide polymorphisms (SNP) rs7756992 A/G and rs7754840 G/C of cyclin-dependent kinase 5 regulatory subunit-associated protein 1-like 1 (CDKAL1) gene with the susceptibility of gestational diabetes mellitus (GDM) has been studied in a group of Bangladeshi women." (PMID 35090536, 2022). "The maternal CDKAL1 gene variants were associated with increased risk of adverse pregnancy outcome, low birth weight and macrosomia, independent of gestational diabetes mellitus." (PMID 40133860, 2025).
melanoma (7 papers, 2018 to 2024). A malignant, usually aggressive tumor composed of atypical, neoplastic melanocytes. "Out of 20 orthologues of human melanoma-associated loci, 12 contained SNPs with p-values < 10–2 in the MeLiM model, and 6 of them had SNPs reaching a p-value < 10–3: CDKAL1 on SSC7, FTO on SSC6, PLA2G6 on SSC5, TMEM38B-RAD23B on SSC1 and SLC45A2 and TERT on SSC16." (PMID 29963229, 2018). "Moreover, comparison of the porcine results to those reported by human melanoma GWAS indicated shared association signals notably at CDKAL1 and TERT loci but also nearby CCND1, FTO, PLA2G6 and TMEM38B-RAD23B loci." (PMID 29963229, 2018). "Yet, CDKAL1 resides only 650kb away from the best SNP ASGA0031451, and was significantly associated with human melanoma in a large-scale GWAS." (PMID 29963229, 2018). "Two exceptions might be the CDKAL1 and TERT melanoma risk loci, that lie near the orthologous SCC7 and SSC16 ulceration-associated regions, respectively." (PMID 29963229, 2018). "A lower SNP coverage in pigs could explain that despite a less significant p-value, CDKAL1 could be a relevant candidate for porcine melanoma, accounting for the SCC7 signal, although more investigation is needed." (PMID 29963229, 2018). "We confirmed the overlapped immunofluorescent signals of CDKAL1 and SALL2 in RMS cells, as well as melanoma, liver cancer, prostate cancer, and stomach cancer." (PMID 36786012, 2023). "We found that the expression levels of CDKAL1 were increased in the population of CSCs and demonstrated that CDKAL1 was required for the maintenance of CSCs‐related traits in RMS as well as the other common cancers, such as melanoma, liver cancer, prostate cancer, stomach cancer, and glioma." (PMID 36786012, 2023).
Crohn disease (4 papers, 2010 to 2020). A gastrointestinal disorder characterized by chronic inflammation involving all layers of the intestinal wall, noncaseating granulomas affecting the intestinal wall and regional lymph nodes, and transmural fibrosis. "We tested whether genes associated with Crohn's disease are also associated with ankylosing spondylitis and confirmed that the two diseases share associations at chromosome 1q32 near KIF21B, STAT3, IL12B, CDKAL1, LRRK2/MUC19, and chromosome 13q14." (PMID 21152001, 2010). "This study of genes associated with Crohn's disease has identified definite genome-wide significant association with AS of SNPs at chromosome 1q32 near KIF21B, and experiment-wise association at five other novel-AS loci including STAT3, IL12B, CDKAL1, LRRK2/MUC19, and at chr13q14." (PMID 21152001, 2010).